VWF (von Willebrand factor)
Diseases named in the same sentence as VWF in open-access papers (continued):
Sharing a sentence is not in itself a finding about the gene and the disease.
Cognitive impairment (9 papers, 2015 to 2025). Abnormal cognition is characterized by deficits in thinking, reasoning, or remembering. "Apart from methodological considerations, release of VWF from damaged endothelial cells in later stages of cognitive impairment may explain why profound cross-sectional associations do not extend to longer term follow-up." (PMID 29615758, 2018). "In this study, we examined cognitive deficits in rats subjected to TBI and correlated changes in the number of CD34+ cells and vWF+ vascular cells in the hippocampus of injured brain tissue and EPCs in the peripheral blood." (PMID 29201537, 2017). "The association between cognitive impairment and non-O blood group is possibly related to the increased levels of FVIII/vWF and other hemostatic factors." (PMID 26042891, 2015). "This indicates that the relationship between VWF levels and neurodegenerative or cognitive impairment may involve non-AD pathways, such as well-established vascular pathway." (PMID 40969184, 2025).
endometriosis (9 papers, 2010 to 2026). The growth of functional endometrial tissue in anatomic sites outside the uterine body. "Another MR study has demonstrated the causal associations between ADAMTS13/vWF and the risk of endometriosis, suggesting the involvement of coagulation factors in endometriosis development." (PMID 38627726, 2024). "A negative causal effect of ADAMTS13 and a positive causal effect of vWF on endometriosis were observed in the FinnGen." (PMID 37226166, 2023). "Conversely, the genetically predicted plasma vWF levels are positively associated with the risk of endometriosis, indicating vWF function as a risk factor for the development of endometriosis." (PMID 37226166, 2023). "In other words, ADAMTS13 is found to have a protective effect associated with endometriosis, while vWF is characterized as a risk factor for the development of the condition." (PMID 37226166, 2023). "In conclusion, our FinnGen cohort results suggest that ADAMTS13 levels are causally associated with a decreased risk of endometriosis, and the positive association observed between vWF and the risk of endometriosis is likely to be causal." (PMID 37226166, 2023). "The findings convincingly support the causal associations between ADAMTS13/vWF and the risk of endometriosis." (PMID 37226166, 2023). "The significant MR result of vWF on the risk of endometriosis was also observed (IVW: OR = 1.26, 95%CI: 1.09–1.46, P = 0.002; WM: OR = 1.29, 95%CI: 1.10–1.51, P = 0.002)." (PMID 37226166, 2023). "Our MR analysis based on GWAS data from large-scale population studies demonstrated the causal associations between ADAMTS13/vWF and the risk of endometriosis." (PMID 37226166, 2023). "Our findings of this MR study confirmed the causal roles of ADAMTS13 and vWF on endometriosis." (PMID 37226166, 2023). "There may be a link between genetically predicted plasma levels of coagulation factors ADAMS13 (A disintegrin and metalloproteinase with thrombospondin motifs) and vWF (von Willebrand factor) and the risk of endometriosis." (PMID 38254632, 2023). "Our results indicate that genetically predicted plasma ADAMTS13 levels were inversely associated with endometriosis, while genetically predicted plasma vWF levels demonstrated a positive causal association with endometriosis, as confirmed in the meta-analysis combining the cohorts." (PMID 37226166, 2023). "The expression profiles of key endoplasmic reticulum stress-related genes, including EPAS1, F8, VCAM1, and VWF, exhibited significant disparities between endometriosis specimens and both adjacent normal endometrial tissues and control endometrial tissues." (PMID 41188339, 2025). "Research has noted that women with endometriosis exhibit a hypercoagulable status characterized by elevated levels of specific coagulation factors, such as fibrinogen and vWF." (PMID 37226166, 2023). "Histological and biochemical data showed increased expressions of vascular endothelial growth factor (VEGF), VEGF receptor-2, cycloxygenase (COX)-2, von Willebrand factor along with angiogenesis during endometriosis progression." (PMID 27695098, 2016). "We also found expressions of von Willebrand factor which is a marker for angiogenesis elevated with progression of endometriosis." (PMID 27695098, 2016). "The results of bioinformatics analysis suggested that EPAS1, F8, VCAM1, and VWF might be highly expressed in endometriosis." (PMID 41188339, 2025). "Heterogeneity tests revealed heterogeneity in endometriosis for three coagulation factors, vWF (IVW: Cochran’s Q = 20.35, Pheterogeneity = 0.041), aPTT (IVW: Cochran’s Q = 16.57, Pheterogeneity = 0.011), and FVIII (IVW: Cochran’s Q = 11.80, Pheterogeneity = 0.003)." (PMID 37226166, 2023). "The findings highlighted that the plasma ADAMTS13 levels have a negative causal effect on endometriosis, whereas the plasma vWF levels have a positive causal effect on endometriosis." (PMID 37226166, 2023).
endometriosis (continued). "However, other coagulation factors (vWF, aPTT, FVIII, FVII, FX, ETP, PAI-1, protein C, and plasmin) had no significant causal effect on endometriosis." (PMID 37226166, 2023).
injury (9 papers, 2012 to 2023). Damage inflicted on the body as the direct or indirect result of an external force, with or without disruption of structural continuity. "Biomarkers of endothelial and alveolar epithelial injury, such as von Willebrand factor (vWF) and soluble intercellular adhesion molecule-1 (ICAM-1), have been associated with pathogenesis and outcome of patients with acute lung injury." (PMID 30359446, 2018). "Moreover, the platelet adhesion molecule von Willebrand factor (VWF) increases during acute APAP-induced liver injury which promotes platelet aggregation and delays tissue repair." (PMID 34298870, 2021). "To test this hypothesis, we studied the role of VWF in AKI using a mouse model of acute ischemia-reperfusion (I/R) kidney injury." (PMID 31594992, 2019). "Similarly, the VWF levels of patients with traumatic brain injury in two previous studies peaked on day 7 and within the second week after entering the ICU." (PMID 24034700, 2013).
renal dysfunction (9 papers, 2014 to 2024). "High VWF levels were associated with mild and severe renal dysfunction, and with micro and macroalbuminuria, in the present study." (PMID 26168189, 2015). "On the other hand, ADAMTS-13 presented increased levels in patients with mild and severe renal dysfunction, which also correlates with an increase in D-dimer and Von Willebrand factor." (PMID 38892211, 2024). "Low magnesium was significantly and strongly associated with increased BMI, heavy drinking, AF, renal dysfunction, use of antihypertensive drugs, HOMA-IR, CRP, IL-6, vWF, cTnT and NT-proBNP." (PMID 29663176, 2018). "Von Willebrand factor levels were increased in patients with mild (P=0.001) and severe (P<0.001) renal dysfunction as compared to the control group." (PMID 26168189, 2015). "VWF plasma levels were elevated in patients with mild and severe renal dysfunction as compared to the control group (P = 0.001 and P < 0.001, respectively)." (PMID 26168189, 2015). "Conversely, a low ADAMTS13 activity/ADAMTS13 Ag ratio was associated with mild and severe renal dysfunction, and with micro and macroalbuminuria, suggesting that the rise in ADAMTS13 Ag levels is not accompanied by a proportional increase in ADAMTS13 activity and VWF cleavage in these patients." (PMID 26168189, 2015). "Therefore, VWF, ADAMST13 and D-Dimer levels may complement each other on the follow-up of renal dysfunction in DM1 patients as well as their risk for cardiovascular disease and progression of renal dysfunction." (PMID 26168189, 2015). "In agreement, this compensatory elevation in ADAMTS13 Ag levels and the increase in ADAMTS13 activity may be responsible for keeping VWF/ADAMTS13 Ag and VWF/ADAMTS13 activity ratios unchanged, as seen in patients with renal dysfunction." (PMID 26168189, 2015).
aneurysm (8 papers, 2016 to 2024). Bulging or ballooning in an area of an artery secondary to arterial wall weakening. "It has been demonstrated that ECs derived from the aortic wall of an aneurysm present decreased levels of VE-cadherin, von Willebrand factor (vWF), and PECAM-1." (PMID 38700707, 2024). "Immunohistochemistry revealed an increased number of vWF+ vessels, mainly in the outer half of the tunica media, in both aneurysms compared with control aortas (p < 0.001), and this was greater in MFS than in non-MFS TAA (p < 0.01)." (PMID 32961817, 2020). "We compared also the mRNA level of SMA, CD31/PECAM, VE-cadherin, and vWF in endothelial cells derived from control aortas and from aneurysms." (PMID 26904289, 2016). "In previous studies, VWF was found to be expressed in aneurysm tissue and colocalized with hepatocyte growth factor (HGF) in the most severe part of the aneurysm-injured wall." (PMID 35637715, 2022). "Double immunofluorescence staining for von Willebrand factor (vWF), expressed in both endothelial cells and platelets (and thus platelet-rich thrombus), and α-SMA, a VSMC marker, showed disruption of the endothelial layer in the aortas with aneurysm." (PMID 39742002, 2024). "Furthermore, scanning electron microscopy, H&E staining and immunofluorescence detection of vWF and CD31 in the necks of aneurysms showed that sitagliptin significantly promoted endothelialization of the aneurysmal neck, while AMD3100 inhibited endothelialization of the aneurysmal neck." (PMID 32038475, 2019). "Expression of the endothelial markers vWF and CD31/PECAM was substantially decreased in endothelial cells from aneurysms; the level of VE-cadherin mRNA was not changed." (PMID 26904289, 2016).
brain infarcts (8 papers, 2014 to 2025). "The results of the present study demonstrated that vWF:Ag concentrations were significantly higher in cerebral infarction patients as compared with the controls (P<0.01), which is in accordance with the results of previous studies on various populations." (PMID 24926346, 2014). "In this setting, chronic cerebral ischemia could further link vWF to cognitive decline via (covert) brain infarcts or cortical micro-infarcts." (PMID 40299555, 2025). "We could show that targeting the early steps of platelet adherence to vessel walls via glycoprotein (GP) Ibα–von Willebrand factor (vWF) interactions can delay progressive brain infarctions by blocking platelet–lymphocyte responses." (PMID 36012752, 2022). "Surprisingly, however, in a model of focal cerebral ischemia, mice that expressed vWF only in platelets developed brain infarcts to the same extent as wt mice, which pointed to the undeniably important role of the platelet-derived vWF in inflammatory processes following transient ischemia." (PMID 33172065, 2020). "On the other hand, after ischemic brain injury, the mice with only platelet vWF and without plasma vWF, had a cerebral infarction size similar to the wild-type mice." (PMID 33096906, 2020).
liver dysfunction (8 papers, 2018 to 2026). "For example, higher preoperative VWF appeared to be negatively associated with post-resection liver dysfunction in patients with HCC undergoing partial hepatectomy, whereas, high post-resection plasma VWF concentrations indicated the early HCC recurrence." (PMID 37950277, 2023). "Recently, von-Willebrand-Factor (vWF) has been shown to correlate with postoperative liver dysfunction (LD)." (PMID 30429491, 2018). "Moreover, ADAMTS-13 is inversely correlated with the severity of liver dysfunction in terms of antigen production and activity, whereas VWF antigen and activity increase, as previously discussed, resulting in the release of high molecular weight VWF (HMWVWF) multimers." (PMID 37443746, 2023). "In addition to rebalanced coagulation there is altered platelet production due to decreased thrombopoietin production by liver, increased von Willebrand factor from low grade endothelial cell activation, and hyperfibrinolysis and dysfibrinogenemia from altered synthetic liver dysfunction." (PMID 33425821, 2020). "Diminished ADAMTS-13 levels are probably attributed to elevated VWF levels, leading to consumption of ADAMTS-13, while liver dysfunction is an adding factor." (PMID 38399555, 2024). "Surprisingly, ADAMTS13-Act was not related to VWF biomarkers or the VWF-Ag/-A ratio, and also similar between different stages of PH and liver dysfunction in our cohort of clinically stable ACLD patients and liver-healthy controls, which add important data to the controversy on ADAMTS13-Act in ACLD." (PMID 37605068, 2023).
Menorrhagia (8 papers, 2015 to 2025). Prolonged and excessive menses at regular intervals in excess of 80 mL or lasting longer than 7 days. "These variants are likely to mediate their effects through increased (VWF) or decreased (F5) blood loss, in women being mainly mediated through menstruation, supported by the finding that factor V Leiden variant protects against menorrhagia." (PMID 33536631, 2021). "vWF activity is expected to be less in women with vWD and consequently menorrhagia as it is the most common presentation." (PMID 34394804, 2021). "von Willebrand factor activity levels were associated with menorrhagia while activated partial thromboplastin time was not." (PMID 34394804, 2021). "A second family member, harboring the same genetic defect in VWF in homozygous state in the absence of anti-thrombin deficiency, suffered from severe bleeding symptoms (severe menorrhagia, hemarthrosis) requiring prophylactic treatment with VWF concentrate." (PMID 33477601, 2021). "Since menarche, at 12 years of age, she has had menorrhagia leading to severe iron deficiency anaemia requiring iron supplementation, repeated red cell transfusions, and on-demand VWF:FVIII factor concentrate including Wilfactin (high-purity plasma derived von Willebrand factor concentrate)." (PMID 25960895, 2015). "The proband experienced several times of severe menorrhagia, had a prolonged APTT, low level of plasma VWF Antigen (2%), and markedly reduced FVIII coagulant activities (2%)." (PMID 34838051, 2021). "Therefore, it sounds reasonable to hypothesize that increase in antiangiogenic endostatin, which also downregulated VWF and several other coagulation factors, during early follicular phase may contribute to the development of menorrhagia—common symptom in women with VWD." (PMID 30629692, 2019). "Therefore, our findings of less vWF activity in women with menorrhagia than those without are consistent with literature and other studies." (PMID 34394804, 2021). "A family history of menorrhagia did not influence a participants vWF activity, p=0.196." (PMID 34394804, 2021). "More specifically, we aimed, firstly, to determine and compare vWF activity and a PTT in women with menorrhagia, the “cases” and women without menorrhagia, the “controls”." (PMID 34394804, 2021).
pancreatitis (8 papers, 2018 to 2025). Inflammation of the pancreas. "Aside from the well-established role in hemostasis, the balance between ADAMTS13 and vWF has been linked to a variety of diseases, such as systemic inflammation, pancreatitis, and multiple sclerosis." (PMID 37226166, 2023). "The pancreatitis activity score system(PASS) score, platelet(PLT) count, von Willebrand factor antigen(vWF:Ag), prothrombin time(PT), activated partial prothrombin time, fibrinogen, thrombin time, antithrombin III(ATIII), plasminogen, serum calcium(Ca) and D-dimer(D-D) were compared." (PMID 41394373, 2025). "Patients who developed severe/necrotizing AP had a median absolute increase of vWF:Ag between day 1 and day 3 of 32% in contrast to patients with non-severe edematous pancreatitis, who experienced a median decrease of 8%." (PMID 35690841, 2022).
pneumonia (8 papers, 2014 to 2026). An acute, acute and chronic, or chronic inflammation focally or diffusely affecting the lung parenchyma, caused by an infection in one or both of the lungs (by bacteria, viruses, fungi, or mycoplasma.). "Similarly, plasma vWF concentrations >648 mU/mL were associated with a 5-fold increase in the odds of severe pneumonia (OR, 5.26 [95% CI, 2.42–11.4]), with good sensitivity (87.0%) but poor specificity (41.7%)." (PMID 24696240, 2014). "Streptococcus pneumoniae, the most common pneumonia pathogen, has been shown to induce Weibel–Palade exocytosis and the release of VWF and interleukin 8 from lung endothelial cells." (PMID 39408067, 2024). "A procoagulant imbalance has also been observed in patients with nosocomial pneumonia; in particular, the VWF/ADAMTS13 ratio was higher in patients with pneumonia than in healthy subjects." (PMID 39408067, 2024). "We measured the levels of four DEmRNAs (F13A1, ITGB3, ITGA2B and VWF) involved in platelet aggregation during SARS-CoV-2 infection in 5 patients with pneumonia and 6 normal donors by RT-qPCR." (PMID 35139909, 2022). "We found that the ITGA2B and VWF were significantly decreased in patients with pneumonia compared with control donors." (PMID 35139909, 2022). "The ability of the most common pneumonia pathogen Streptococcus pneumoniae to induce exocytosis of Weibel–Palade bodies and VWF and interleukin 8 (IL-8) release from pulmonary endothelial cells has been reported." (PMID 35215805, 2022). "NGAL/Lpc-2, CRP, and von Willebrand factor (vWF) levels were shown to be significantly increased in children with severe pneumonia." (PMID 31183362, 2019). "Compared to children with normal x-ray, children with end-point pneumonia had significantly higher C-reactive protein, procalcitonin and Chitinase 3-like-1, while those with other infiltrates had elevated procalcitonin and von Willebrand Factor and decreased soluble Tie-2 and endoglin." (PMID 26366571, 2015). "Different definitions of pneumonia may explain the discordant vWF results." (PMID 26366571, 2015). "Lpc-2, CRP, and vWF levels were significantly higher in children with severe pneumonia than in those with nonsevere pneumonia." (PMID 24696240, 2014).
cardiomyopathy (7 papers, 2017 to 2025). A disease of the heart muscle or myocardium proper. "Similarly, in cats with ATE and cardiomyopathy, the elevation in circulatory vWF has been suggested to be associated with endothelial damage." (PMID 33925795, 2021). "LA samples from cardiomyopathic cats with LAE and clinical signs (CHF and ATE), but not those from subclinical cardiomyopathic cats had increased endocardial vWF protein compared to control cats, which suggests an association of endocardial vWF elevation with an advanced stage of cardiomyopathy." (PMID 33925795, 2021). "Confocal microscopy and quantitative immunohistochemistry using antibodies against VWF showed that VWF signal is significantly higher in all patients with cardiomyopathies compared to controls." (PMID 38381272, 2024). "The expression of VWF in the control group and in cardiomyopathies was studied at the protein level." (PMID 38381272, 2024). "Compared to the control group, the VWF level is significantly increased in all patients with cardiomyopathies." (PMID 38381272, 2024). "This is the first study to quantify and characterise vWF in the LA endocardium and LA thrombi from cats with cardiomyopathy at different stages of their disease process." (PMID 33925795, 2021). "For that reason, different cardiomyopathy phenotypes may influence the functional capacity of vWF in cats." (PMID 40509097, 2025). "We studied the expression of one such protein called von Willebrand Factor in the left atrium of cats with and without cardiomyopathies and at different stages of disease severity." (PMID 33925795, 2021). "Cats with cardiomyopathy without ATE and those with ATE were found to have normal and increased vWF : Ag, respectively." (PMID 34590754, 2021).